JMJD6 (jumonji domain containing 6, arginine demethylase and lysine hydroxylase)
Diseases named in the same sentence as JMJD6 in open-access papers (continued):
Sharing a sentence is not in itself a finding about the gene and the disease.
cancer (continued). "To gain more mechanistic insights into the role of JMJD6 in carcinogenesis, we analyzed the expression of JMJD6 across a set of cancer types on the website for cBioPortal for Cancer Genomics." (PMID 29187213, 2017). "The physiological context of the described molecular functions is considered and recently described novel roles for JMJD6 in cancer and immune biology are reviewed." (PMID 28360925, 2017). "In conclusion, the catalytic activities of JMJD6 are involved in cancer tumorigenesis, and we can expect that the discovery of more substrates will emphasize its link with cancer." (PMID 27556302, 2016). "Such efforts will provide a better understanding of the molecular activity and biological function of JMJD6 and will benefit the development of biomolecules for the diagnosis, prognosis, and treatment of cancers." (PMID 24667498, 2014). "We hypothesize that JMJD6 drives radioresistance in NSCLC by epigenetically reprogramming cancer cells towards a stem-like state." (PMID 41320721, 2025). "Furthermore, our pan-cancer data analysis revealed that JMJD6 exhibits a significant intronic APA event that is common to seven different cancer types." (PMID 39349823, 2024). "To test this hypothesis, we used DepMap data that included 225 metabolites in 928 cancer cell lines from over 20 lineages, and analyzed the correlation of each metabolite with JMJD6 gene dependency." (PMID 38488852, 2024). "Notably, several studies have investigated the role of JMJD6 in cancer biology but have suggested contradictory models for its function in cancer pathogenesis." (PMID 39349823, 2024). "JMJD6 has pleiotropic functions in normal physiology and in cancer." (PMID 38488852, 2024). "Our study uncovered two cancer-relevant alternative splice isoforms of JMJD6 that regulate 5-Hyl proteins in distinct cellular pathways, providing unique insights into the functional roles of JMJD6 alternative splicing in transcriptional regulation and cellular development." (PMID 39421203, 2024). "Likewise, JMJD6 is also frequently altered in cancers with high expression and poor outcomes reported across many cancer contexts, potentially through mechanisms that include dysregulation of 7SK snRNP function." (PMID 36754845, 2023). "Thus, inhibiting JMJD6 activity was recognized as a promising solution for the treatment of JMJD6-involved cancers." (PMID 37880710, 2023). "Therefore, on the basis of above study, we further investigated the effect of JMJD6 inhibitor on cancer." (PMID 37880710, 2023). "Furthermore, elevated expression of JMJD6 can maintain cancer stemness properties, and SKLB325, an inhibitor of JMJD6, can effectively impede the progression of cancer." (PMID 37880710, 2023). "The relationship between JMJD6 and prognosis varied across different types of cancers." (PMID 37488513, 2023). "Recent studies revealed that JMJD6 is closely connected with cancer development and prognosis." (PMID 35359945, 2022). "However, how JMJD6 regulates epigenetic events and immune responses to affect the progression of malignant tumors still needs further research." (PMID 35359945, 2022). "Interestingly, inhibitors of JMJD6 have been developed and have shown repressive effects on some types of cancers." (PMID 35327545, 2022). "We believe that JMJD6 has great potential as a novel target for cancer immunotherapy." (PMID 35359945, 2022). "Bioinformatics analyses aimed at describing the immune role of JMJD6 are pivotal in determining different types of cancers that might benefit from the anti-JMJD6 immunotherapy." (PMID 35359945, 2022). "Owing to the crucial roles of JMJD6 in different cancers, inhibitors of JMJD6 may have potential antitumor effects." (PMID 35359945, 2022). "Except for SKLB325, WL12, and compound 7p, the other four HIF prolyl hydroxylase inhibitors (Vadadustat, AKB-6899, GSK1278863/daprodustat, and panobinostat) may be potential JMJD6 inhibitors for cancer therapy." (PMID 35359945, 2022).
cancer (continued). "PFK-2/FBPase-2, ATIC, LTA4H and Jmjd6 are four multifunctional enzymes with a proven relevant role in the proliferation and/or survival of cancer cells, and their inhibition can increase the life expectancy of some cancer patients." (PMID 35056904, 2021). "Overall, the existing evidence suggests that the simultaneous inhibition of both the demethylase and hydroxylase activities of JMJD6 may be a promising strategy for effective cancer therapy." (PMID 35056904, 2021). "However, a large number of preclinical and clinical experiments are needed to verify the effectiveness of JMJD6 inhibition in cancer therapy." (PMID 31961032, 2020). "By virtue of its important role in cancer, JMJD6 stands as an attractive therapeutic target." (PMID 31961032, 2020). "Currently, the increasing trend of documents showed the essential contribution of histone demethylases such as JARID1, KDM4, LSD1, KDM6B, KDM6A, KMD3, KDM5, and Jumonji domain–consisting of protein 6 (JMJD6) to the cancer stem cell phenotype in several kinds of cancers." (PMID 32280305, 2020). "Indeed, TCGA SpliceSeq data showed a significant but relatively small decrease in Jmjd6-Ex5 in post mortem tissue of BRCA, COAD and LUSC, which links JMJD6-2 to cancer progression." (PMID 32927736, 2020). "JMJD6 is known to have a multitude of functions and is implicated in several cancers, however, to our knowledge, no one has examined the function of U2AF65 or JMJD6 in detail across different tissues." (PMID 32039444, 2020). "Although the mechanisms through which JMJD6 promotes cancer progression remain unclear, several mechanisms have been proposed in published studies." (PMID 31961032, 2020). "Therefore, JMJD6 plays a role in the development of oral cancer, in part because it serves as a molecular determinant of cancer stem cell phenotype." (PMID 31961032, 2020). "In particular, we focused on the role of JMJD6 in cancer progression and candidate mechanisms in order to highlight that JMJD6 may represent an attractive target for a new generation of anticancer drugs." (PMID 31961032, 2020). "JmjC domain-containing protein 6 (JMJD6) is a 2-oxoglutarate (2OG)-dependent oxygenase linked to various cellular processes, including splicing regulation, histone modification, transcriptional pause release, hypoxia sensing, and cancer." (PMID 31147442, 2019). "Multiple studies demonstrated the involvement of JMJD6 in cancer pathogenesis." (PMID 28587176, 2017). "Finally, we will discuss Jmjd6 functions in a physiological context and review its recently described novel roles in cancer and immune biology." (PMID 28360925, 2017). "Indeed, the expression profile of JMJD6 has been investigated by several groups in different types of cancers." (PMID 27556302, 2016). "Likewise, JMJD6 is also overexpressed in several cancers, such as breast, oral, lung and colon cancer." (PMID 27556302, 2016). "Nevertheless, overexpression of JMJD6 in several cancers may trigger excessive demethylation and/or hydroxylation of several substrates involved in tumorigenesis." (PMID 27556302, 2016). "Consistently, we detected overexpression of JMJD6 in carcinomas from multiple tissues." (PMID 24667498, 2014). "In the JMJD6-repressed subset, a large number of genes were related to cancer function." (PMID 22621393, 2012). "JMJD6 has ability to promote cancer cell proliferation and motility, which in turn may augment cancer virulence in vivo." (PMID 22621393, 2012). "JMJD6 is important in development and JMJD6 catalysis may promote cancer." (PMID 40046450, 2025). "However, the exact mechanism of JMJD6 in MYC-driven cancers remains elusive." (PMID 38488852, 2024). "Despite ample evidence supporting the pivotal role of JMJD6 in the treatment and prognosis of patients with cancer and its relevance in managing ischemic cardiovascular diseases, a noticeable lack of research is observed regarding the autoantibodies against JMJD6." (PMID 38732153, 2024).
cancer (continued). "Abnormal expression of JMJD6 may contribute to the development of many diseases, such as neuropathic pain, foot-and-mouth disease, gestational diabetes, hepatitis C, and various types of cancer." (PMID 37488513, 2023). "Therefore, our findings may expand our knowledge of the functions of Jmjd6 in animal development as well as multiple human diseases including cancer." (PMID 31361752, 2019). "Though alterations in the sequence of JMJD6 have not been identified in cancer, its overexpression is associated with various cancers, suggesting that it could constitute targets for therapeutic strategies." (PMID 28587176, 2017). "However, at this stage it still needs to be established whether amplification of Jmjd6 and c-Myc driven initiation or progression of tumorigenesis might be a more general mechanism across different types of cancers." (PMID 28360925, 2017). "Though the exact mechanisms of JMJD6-mediated carcinogenesis are not yet fully understood, these observations lend support to the existing hypothesis implicating JMJD6 in the pathogenesis of various cancers." (PMID 28587176, 2017). "Identification of JMJD6 as a gene that cooperates with Myc to enhance tumorigenesis could provide a novel therapeutic target for breast and other cancers where Myc is an essential driver of tumorigenesis, since to date no successful therapies directly targeting Myc have been developed." (PMID 27081402, 2016). "However, very little is known about the role of JMJD6 in cancer and the molecular pathways that may impinge on disease initiation and prognosis." (PMID 22621393, 2012). "As JMJD6 has long been identified as a demethylase for histone H4 at arginine 3 (H4R3), and H4R3me2 is a key epigenetic event in cancer, the binding of symmetric H4R3me2 on A549 genome was also assessed." (PMID 41320721, 2025). "Further, we show that JMJD6 is correlated with the anti-cancer activity of indisulam, a ‘molecular glue’ that degrades splicing factor RBM39, which complexes with JMJD6." (PMID 38488852, 2024). "The present study for the first time identified JMJD6 (Jumonji domain-containing 6) as a novel regulator of TAM activation which would serve as a therapeutic target and combination partner for ICBs in cancer." (PMID 37567973, 2023). "Many histone demethylases have been proven to promote the genesis and development of cancer, such as KDM3A, KDM4A, KDM4D, and JMJD6." (PMID 34980950, 2021). "Overall, based on the protein levels, it appears that JMJD6 and YBX1 establish a feed-forward loop of expression that may augment their overlapping functions in cancer cells." (PMID 40855961, 2025). "This establishes a novel IR-JMJD6-EHF signaling axis in EHF, once transcriptionally activated by JMJD6, acts as a pioneer factor that opens up chromatin and facilitates the expression of a broader network of genes involved in cancer cell stemness and survival." (PMID 41320721, 2025). "JMJD6 knockout greatly reduced the production of TCA cycle intermediates (i.e. oxoglutarate, fumarate) and nucleoside triphosphate (ATP, CTP, GTP), indicating that JMJD6 is a key bioenergetic regulator in cancer cells." (PMID 38488852, 2024). "In addition to complexing together, JMJD6 and RBM39 exhibit significant correlation of co-dependency in cancer cells, namely, cancer cells have similar dependency on JMJD6 and RBM39 for survival." (PMID 38488852, 2024). "Inability to target the enhanced pre-mRNA splicing of metabolic genes in MYC-driven cancer cells by pharmacological inhibition of JMJD6 is another limitation, due to lack of selective and potent JMJD6 inhibitors." (PMID 38488852, 2024). "Although the exact mechanism by which JMJD6 promotes tumorigenesis and progression has not been elucidated, the interaction of JMJD6 with cancer-related signaling pathways has been identified as one of the potential mechanisms." (PMID 37488513, 2023).
cancer (continued). "In this regard, inhibitors of JMJD5, JMJD6, and JMJD7 could be effective anticancer drug targets to treat different cancers." (PMID 35327545, 2022). "Although several studies have suggested a role for Jmjd6 in tumorigenesis, the primary pathways and targets of Jmjd6 that might promote development or progression of cancer are not clear." (PMID 28360925, 2017). "Since no peptide sequence corresponding to antibodies from other cancer patients or from a healthy control produced any matches to the JMJD6 protein, the p-value calculated by Fisher's exact test is p = 0.0009, suggesting that the two peptides mimic real sequential epitopes of the protein." (PMID 20711419, 2010). "However, JMJD6 isoform-specific patterns in cancer have not been analyzed yet." (PMID 32927736, 2020). "Additionally, no JMJD6 inhibitors have been developed and applied to targeted cancer research." (PMID 31637004, 2019). "Notably, JMJD6 regulated the alternative splicing of genes that are related to several KEGG signaling pathways, including MAPK signaling pathway, endocytosis, amino sugar metabolism, proteoglycans in cancer, 2-oxocarboxylic acid metabolism, and ubiquitin-mediated proteolysis." (PMID 29187213, 2017).
infection (13 papers, 2014 to 2025). The state of being infected such as from the introduction of a foreign agent such as serum, vaccine, antigenic substance or organism. "IRF3 expression diminished with IRF3 phosphorylation at 4 h post-infection of SeV in JMJD6-overexpressing HEK293T cell lines." (PMID 33684176, 2021). "Immunofluorescent microscopy used to study the movement of JMJD6 from cell membrane to nucleus after infection with JMJD6-FMDV showed failure of internalization of JMJD6 by the mutant virus in the presence of hypertonic sucrose, while nystatin treatment did not impede the JMJD6 internalization." (PMID 28587176, 2017). "The cumulative findings in non-RGD-containing variants of FMDV serotypes O, A, C have proposed that the positively charged residues at receptor-related protein-binding sites might also act as one of the molecular determinants for JMJD6-mediated infection of pgsD-677 cells." (PMID 33050303, 2020). "For example, two novel intergenic splicing events occurred between exons of SRSF2, JMJD6 and MXRA7 late in infection." (PMID 25989971, 2015).
neurodegenerative disease (1 paper, 2023). A disorder of the central nervous system characterized by gradual and progressive loss of neural tissue and neurologic function. "JMJD6 is expressed in many tissues throughout the body, including the brain according to the Human Protein Atlas158, but very little is known about its role in the brain or in neurodegenerative disease." (PMID 37188718, 2023).
neurological disorders (1 paper, 2022). "Indeed, identified genes are implicated in viral (SEC14L1, JMJD6, SRSF2, TMPRSS2, MX1, MX2) bacterial (COL8A1, SPIRE1), and neurological disorders (MFSD11, METTL23, CTTNBP2, BACE2, IMPA2, MPPE1 and GNAL), or in the functions of the Golgi complex (MGAT5B), organelle where viral envelope is occurred." (PMID 35581286, 2022).
JMJD6 also shares sentences with these, for which no sentence is quoted: glioblastoma (5 papers); chronic hepatitis B virus infection (2); esophageal squamous cell carcinoma (2); Lewis lung carcinoma (2); Lung Squamous Cell Carcinoma (2); acute myocardial infarction (1); acute pancreatitis (1); alcoholic liver diseases (1); autoimmune disease (1); breast ductal carcinomas (1); cardiovascular disease (1); clear cell renal cell carcinoma (1); diabetes mellitus (1); gastric cancer (1); head and neck squamous cell carcinoma (1); hepatitis C (1); HIV-1 infection (1); inflammation (1); Iron Deficiency (1); lentivirus infection (1); liver fibrosis (1); Obesity (1); pancreatitis (1); preeclampsia (1); pulmonary diseases (1); rectal adenocarcinomas (1); serous ovarian cancer (1); thyroid cancer (1); transient ischemic attack (1); viral hepatitis (1).